VIM (vimentin)
Diseases named in the same sentence as VIM in open-access papers (continued):
Sharing a sentence is not in itself a finding about the gene and the disease.
cataract (12 papers, 2011 to 2025). Partial or complete opacity of the crystalline lens of one or both eyes that decreases visual acuity and eventually results in blindness. "VIM: A handful of mutations in the gene for the ubiquitous cytoskeletal protein vimentin (VIM) on chromosome 10p have been associated with autosomal dominant cataract." (PMID 38927721, 2024). "Congenital cataracts can be caused by vimentin mutations, for example, the E151K (VIMWT/E151K) mutation in the vimentin rod domain." (PMID 24142690, 2013). "Previous studies have suggested that the αB-R120G mutation causes DRM and cataracts due to faulty interactions between αB-crystallin and intermediate filament proteins such as vimentin." (PMID 21445271, 2011). "Vimentin (UniProt ID: P08670) is an intermediate filament protein prominently expressed in lens fiber cells to connect the cytoskeleton to cell membranes, and one missense mutation encoding this protein causes pulverulent cataracts." (PMID 40649110, 2025). "In addition to the D-galactose-induced cataract model, other congenital cataract models also show increased senescence of LECs, such as heat shock 4-deficient mice and vimentin-deficient mice." (PMID 36662053, 2022). "Low levels of vimentin are normally found in the epithelium of the lens, patients with cataracts, however, show an increased expression of vimentin in lens epithelial cells." (PMID 30248895, 2018). "At the organismal level, vimentin knockout was connected to cataracts, hyperactivity, impaired balance, impaired coordination, and increased anxiety-related responses." (PMID 30248895, 2018). "This study evaluated whether glucocorticoid treatment can induce changes in vimentin through specific GR activation in glucocorticoid-induced cataracts of the rat lens." (PMID 21245955, 2011). "Based on a model of steroid-induced cataract from our previous study, the present study focuses on whether changes in vimentin can be induced in vitro through specific GR activation in glucocorticoid-induced cataracts of the rat lens." (PMID 21245955, 2011). "This study also finds that vimentin levels in LEC sections were both higher in cataract patients with and without DM." (PMID 32218152, 2020). "Furthermore, vimentin, a protein highly expressed in EMT, is overexpressed in transgenic mice cataracts." (PMID 29888254, 2018).
chondrosarcoma (12 papers, 2007 to 2024). A malignant cartilaginous matrix-producing mesenchymal neoplasm arising from the bone and soft tissue. "Chondroblastic OS is positive for vimentin, EMA, S100, and rarely positive for cytokeratin, whereas chondrosarcoma is positive for vimentin and S100." (PMID 38845795, 2024). "Retarded cell migration was accompanied by decreases in the expression of N-cadherin and vimentin in chondrosarcoma cells, and the addition of Ca2+ abolished both retarded cell migration and decreased N-cadherin expression." (PMID 35499815, 2022). "CaCl2 also completely reversed the melatonin-induced inhibition of migration in both cell lines, as well as the inhibition of N-cadherin and vimentin expression induced by melatonin in chondrosarcoma cells after 8 h of treatment." (PMID 35499815, 2022). "Immunohistochemistry showed that vimentin was expressed in 25 cases of dedifferentiated chondrosarcoma, with positive chondrosarcoma S-100 component and positive dedifferentiated chondrosarcoma SATB2." (PMID 33588810, 2021). "In line with the in vitro data, ATO increased the E-cadherin expression and decreased the p-Stat3, vimentin and N-cadherin expression in tumors formed by chondrosarcoma cells." (PMID 27576314, 2016). "Furthermore, while the EMT markers including Slug, MMP9, MMP2, CD44, N-Cadherin, and vimentin were suppressed by BTZ concomitant increased expression of E-Cadherin was detected in chondrosarcoma cells." (PMID 33674562, 2021). "Primary and metastatic chondrosarcoma of lung have been documented, and the multilobular neoplasm with chondroid and myxoid matrix which is positive to Vimentin and S-100, negative for epithelial markers might cause the confusion with EMC." (PMID 22925697, 2012). "The immunophenotype of chondrosarcomas is typically positive for vimentin and S-100 but without the expression of epithelial markers, such as keratin or EMA." (PMID 32176085, 2020). "β-Catenin, p-β-catenin, N-cadherin and vimentin are well established as indicators of EMT, and accordingly, the poor expression of β-catenin in chondrosarcoma cells of the miR-129-5p group has been observed, which further suppressed the cell proliferation, migration and promoted apoptosis." (PMID 31649488, 2019). "Immunohistochemistry is not helpful in distinguishing chondrosarcoma from CMF because both tumors are known to express vimentin and S-100 protein." (PMID 18036245, 2007). "Additionally, we found expression of genes such as Collagen, type I, alpha 1 (COL1A1), Exostoses (multiple) 1 (EST1), Exostoses (multiple) 2 (EXT2), Vimentin (VIM), and Osteoprotegerin (TNFRSF11B), which are known to be involved in development of conventional chondrosarcomas." (PMID 22448124, 2012).
cyst (12 papers, 2011 to 2025). A sac-like closed membranous structure that may be empty or contain fluid or amorphous material. "Our results showed that SMA and vimentin is already upregulated at P7, before detectable cyst formation, suggesting that the fibrotic response is triggered before cyst formation by signals from defective epithelial cells in this model." (PMID 36920028, 2023). "Increased renal expression of the matricellular protein periostin is accompanied by upregulation of vimentin, which leads to increased mTOR activity, cell proliferation, cyst growth, interstitial fibrosis and acceleration of decline in renal function." (PMID 34206927, 2021). "Immunohistochemistry shows strong staining for cytokeratin in the cyst linings and for vimentin in the subepithelial cells." (PMID 27066288, 2016). "Vimentin expression was prominent in cyst lining epithelia in control PCK kidneys at study termination." (PMID 26136112, 2015). "Then the cyst-derived cells epithelia were detected by immunocytochemistry with cytokeratin antibody, vimentin antibody, E-cadherin antibody and α-SMA antibody." (PMID 22174924, 2011). "Vimentin expression is overall low in both plasma and cyst fluid EV." (PMID 37414831, 2023). "Therefore, there is a possibility that the vimentin-rich ring surrounding the cyst in the described epitheliocystis lesion might act as antigenic target for other immune cells in epitheliocystis lesions." (PMID 35336202, 2022). "Furthermore, HOVs-cyst-1 cells were positive for the expression of both cytokeratin and vimentin, suggesting that some of these cells may have undergone epithelial-mesenchymal transition." (PMID 35326657, 2022). "Further evaluation of CK-19, S100A13 and VIM was performed by ELISA using non-depleted cyst fluid from the extended material of cPTC and benign cystic thyroid lesions as well as cystic reference cases." (PMID 25978681, 2015).
ependymoma (12 papers, 2010 to 2024). A WHO grade II, slow growing tumor of children and young adults, usually located intraventricularly. "We used vimentin (Vim) as an ependymoma marker and alpha-smooth muscle actin (SmA) as a fibroblast marker to characterize the media’s effects on cell selection from the primary tumor tissue." (PMID 37508868, 2023). "Based on morphological and immunohistochemical characteristics of tumor cells that expressed glial fibrillary acidic protein (GFAP), S-100, and vimentin, the tumor was diagnosed as an ependymoma." (PMID 34716641, 2021). "Inside the list of proteins identified by top-down approach, a separate discussion was devoted to the diverse peptide fragments of GFAP and vimentin and of their citrullinated forms naturally occurring in the ependymoma tissue intact proteome." (PMID 32183175, 2020). "Improved PFS following ependymoma resection has been associated with a number of other tumor specific characteristics including lower Ki-67%, lower tumor grade, Vimentin negative tumors, absence of MYCN amplification, and an identifiable tumor plane intraoperatively." (PMID 38438766, 2024). "LINC00899 knockdown in spinal ependymoma cells elevated levels of RBL2, p21, p27 and Bax; decreased levels of FoxO, Bcl-2, vimentin and annexin; reduced cell proliferation, migration and invasion; and enhanced apoptosis." (PMID 31739288, 2019). "Immunological staining with GFAP and vimentin is very helpful for the differential diagnosis of ependymomas from other non-ependymal tumors, such as astrocytic and choroid plexus tumors, and also in differentiating between the various grades of ependymomas." (PMID 32612806, 2019). "Tanycytic ependymoma stains positive for GFAP and vimentin but rarely stains S-100." (PMID 23476839, 2013).
gastrointestinal stromal tumor (12 papers, 2006 to 2025). "We used TEM as well as immunohistology for markers that have been described as highly specific for ICLCs such as vimentin, c-Kit and CD34, as well as PDGFRα, a marker for gastro-intestinal stroma tumor (GIST), which originates from ICLCs." (PMID 27764183, 2016). "In a case of gastrointestinal stromal tumor, the immunoreactivity for vimentin was also not detected by ICC but was detected by IHC." (PMID 36851457, 2023). "The tumor cells are often positive for CD34, CD99, vimentin and BCL-2, and negative for CD117 (in gastrointestinal stromal tumors), smooth muscle actin (SMA) and desmin (in smooth muscle tumors) and S-100 protein (in nerve sheath tumors)." (PMID 25884588, 2015). "Immunohistochemical analysis showed that the tumors were positive for vimentin, WT1, progesterone receptor (PR), and variably for estrogen receptor (ER), CD56, inhibin, and calretinin, while being negative for markers of epithelial, melanocytic, and gastrointestinal stromal tumors." (PMID 40828576, 2025). "Bcl-2 and vimentin are typically immunoreactive in SFTs in addition to CD34 and STAT6, but SMA and desmin (a marker for myocytes), S-100 and synaptophysin (a marker for perineural tissue), or c-kit (a marker for gastrointestinal stromal tumors) are generally negative." (PMID 39435031, 2024).
leukemia (12 papers, 2012 to 2025). A malignant (clonal) hematologic disorder, involving hematopoietic stem cells and characterized by the presence of primitive or atypical myeloid or lymphoid cells in the bone marrow and the blood. "Associated with poor overall survival (OS), leukemia-free survival and vimentin expression." (PMID 33195421, 2020). "Upon contact with leukaemia cells, human choroid plexus fibroblasts acquired a cancer‐associated fibroblast phenotype, with an increased expression of α‐SMA and vimentin as well as pro‐inflammatory factors." (PMID 32686161, 2020). "Cluster B near the center of the CIM is made up largely by leukemia lines, which exhibit low expression of both VIM and CDH1 and very low expression of most of the migration-related genes." (PMID 22570691, 2012). "Changes in vimentin filaments has been reported in dox treated leukemia cells." (PMID 23128467, 2013). "Circ-vimentin is upregulated in AML patients and its elevated expression is an independent poor prognostic factor for OS and leukemia-free survival (LFS) in AML patients." (PMID 33195421, 2020). "In leukemia, it has been speculated that vimentin acts as a negative regulator of apoptosis and confers increased stress resistance, promoting cell survival." (PMID 38672531, 2024). "To explore the attenuated LatB responsiveness of NIH-3T3 fibroblasts compared to HL-60 leukemia cells, we reasoned that NIH-3T3 cells express high levels of the intermediate filament protein vimentin that may protect the cells from excessive deformations when filamentous actin is depolymerized." (PMID 36053000, 2022). "While leukemia did not affect the number of mesenchymal stem/stromal cells (MSCs), PDGFRα+Sca-1+ (PαS) mesenchymal cells, CXCL-12 abundant reticular cells and vimentin+ fibroblasts, we observed significantly lower numbers of endothelial and osteoblastic cells." (PMID 29740160, 2018).
meningitis (12 papers, 2013 to 2023). A disorder characterized by acute inflammation of the meninges of the brain and/or spinal cord. "In summary, all the findings in this study indicate that the pathogenic features of S. suis meningitis are driven by specific interactions between the meningitic virulence factor SssP1 and its primary receptor vimentin." (PMID 35853077, 2022). "For example, the BspC of Group B Streptococcal interacts with vimentin to promote adherence to brain endothelium to cause meningitis." (PMID 35853077, 2022). "The surface proteins of bacterial pathogens play critical roles in causing meningitis via the interaction with the host components (such as the vimentin)." (PMID 35853077, 2022). "A BspC-deficient mutant was unable to cause meningitis within a murine model, while vimentin-deficient mice were protected from infection by wildtype GBS." (PMID 33329493, 2020). "BspC itself induced meningitis-associated inflammation, as discussed in the immune signaling section, and the BspC-vimentin interaction was also necessary for disease progression." (PMID 33329493, 2020). "Vimentin deficient mice also showed resistance to Streptococcus agalactiae induced meningitis." (PMID 34198868, 2021). "Similarly, while our study was underway, it was reported that another bacterium capable of causing meningitis, L. monocytogenes, uses InlF to interact with vimentin to promote brain invasion." (PMID 31181121, 2019). "A pull-down analysis identified vimentin as the potential receptors of SssP1 during meningitis and following Far-Western blot results confirmed this ligand-receptor binding mediated by the NR2 (the second nonrepeat region) region of SssP1." (PMID 35853077, 2022). "This overall observation underscores the significance of host cell surface vimentin interactions in microbial pathogenesis and markedly improves our understanding of host barrier penetration during meningitis." (PMID 35853077, 2022). "We recently demonstrated that GBS surface adhesin, BspC, interacts with host vimentin to initiate brain penetration and the development of meningitis." (PMID 35316308, 2022). "The BspC-vimentin interaction is required for development of meningitis; therefore, this interaction represents an ideal candidate to be targeted for anti-virulence therapy." (PMID 35316308, 2022). "Here, we describe the role of the GBS surface factor, BspC, in promoting meningitis and discover the host ligand for BspC, vimentin, which is an intermediate filament protein that is constitutively expressed by endothelial cells." (PMID 31181121, 2019). "The BspC gene has been found to interact with host vimentin to promote bacterial adherence to the brain endothelium and inflammation in the in vivo and in vitro models of meningitis, which also leads to the enhanced penetration of the BBB and the occurrence of meningitis." (PMID 37895067, 2023). "Importantly, BspC interacts with vimentin, and vimentin-null mice are protected from S. agalactiae infection, suggesting that the vimentin–BspC interaction is important in the pathogenesis of meningitis." (PMID 32630064, 2020). "Vimentin, which is a novel NF-κB regulator, is the primary receptor for the major Escherichia coli K1 virulence factor IbeA that contributes to the pathogenesis of neonatal bacterial sepsis and meningitis (NSM)." (PMID 27657497, 2016). "The release of P65 and the adhesion molecules ICAM-1 and CD44 into CSF were all augmented by E44 infection and suppressed by both vimentin deficiency and IbeA deletion, which confirmed IbeA-vimentin interaction could aggravate the inflammatory response in E. coli meningitis." (PMID 27657497, 2016). "The interaction between vimentin and BspC of GBS promotes adhesion to BMECs and the development of meningitis." (PMID 35921364, 2022).
meningitis (continued). "Suppose all these SRR proteins from diverse bacterial species have similar capacities to interact with the vimentin of BBB, which will significantly promote the exploration of the meningitis pathogenesis in a broader range of bacterial pathogens." (PMID 35853077, 2022). "Taken together these results indicate the importance of vimentin in GBS dissemination into the brain and meningitis disease progression." (PMID 31181121, 2019). "The increased levels of vimentin in the LOH infants must be a direct consequence of infection affecting the brain but the lack of GFAP in LOH indicates that the source is unlikely to be astroglial and may be microglial, endothelial or leptomeningeal since many patients present with meningitis." (PMID 24351234, 2013).